OR2J3 (olfactory receptor family 2 subfamily J member 3)
Description:
Odorant receptor involved in the detection of the flavor compound cis-3-hexen-1-ol (C3HEX), a compound typically described as 'green grassy' or the smell of 'cut grass'.
Synonyms: OR6-6; 6M1-3; C3HEXS; HS6M1-3; OR6-16; OR6.3.6; ORL671
Tractability: Antibody: its Gene Ontology location is reachable by antibodies, with high confidence; UniProt places it where antibodies can reach, with medium confidence; UniProt predicts a signal peptide or a membrane-spanning region.
Gene: Protein-coding gene on chromosome 6 (29,108,058 to 29,114,770, forward strand). Ensembl gene ENSG00000204701.
Subcellular location: Cell membrane
Pathways (Reactome):
Sensory Perception: Expression and translocation of olfactory receptors; Olfactory Signaling Pathway
Gene Ontology:
Molecular function: olfactory receptor activity; G protein-coupled receptor activity
Biological process: detection of chemical stimulus involved in sensory perception of smell; G protein-coupled receptor signaling pathway
Cellular component: plasma membrane; membrane
Genetic constraint (gnomAD): Loss-of-function variants: 13 observed, 18.78 expected, observed/expected ratio (o/e) 0.69, 90% interval 0.45 to 1.1. The upper end of that interval is the gene's LOEUF score, 1.1, which puts it in group 4 of 6, group 1 being the genes least tolerant of losing a copy. Missense variants: 321 observed, 378.84 expected, observed/expected ratio (o/e) 0.85, 90% interval 0.77 to 0.93. Synonymous variants: 142 observed, 142.51 expected, observed/expected ratio (o/e) 1, 90% interval 0.87 to 1.14.
Homologues: Orthologues: chimpanzee OR2J3 (98% identical), macaque OR2J3 (96% identical). Paralogues in human: OR2J1 (88% identical), OR2J2 (87% identical), OR2B6 (58% identical), OR2B2 (58% identical), OR2G3 (57% identical), OR2C3 (56% identical), OR2H2 (56% identical), OR2W3 (56% identical), OR2B3 (55% identical), OR2H1 (55% identical), OR2W1 (55% identical), OR2G2 (55% identical), and 80 more.
Diseases named in the same sentence as OR2J3 in open-access papers:
OR2J3 is named in the same sentence as 2 diseases in open-access papers, as found by Europe PMC text mining. Sharing a sentence is not in itself a finding about the gene and the disease. The quoted sentences say what the papers report.
non-small cell lung carcinoma (1 paper, 2022). A group of at least three distinct histological types of lung cancer, including non-small cell squamous cell carcinoma, adenocarcinoma, and large cell carcinoma. "Another study found that the activation of OR2J3 induces apoptosis and inhibits cell proliferation and migration in non-small-cell lung cancer cell lines." (PMID 35620002, 2022).
OR2J3 also shares sentences with these, for which no sentence is quoted: tumor (2 papers).